DNAH11 (dynein axonemal heavy chain 11)
Description:
Force generating protein required for cilia beating in respiratory epithelia (By similarity). Produces force towards the minus ends of microtubules (By similarity). Key component of dynein, a family of motor proteins essential for movement along microtubules (By similarity). Dynein has ATPase activity; the force-producing power stroke is thought to occur on release of ADP (By similarity). Required for structural and functional integrity of cilia (By similarity).
Synonyms: Dnahc11; DPL11; CILD7; DNAHBL; DNHBL
Tractability: Antibody: its Gene Ontology location is reachable by antibodies, with medium confidence. PROTAC: ubiquitination databases record sites on it.
Gene: Protein-coding gene on chromosome 7 (21,543,039 to 21,901,839, forward strand). Ensembl gene ENSG00000105877.
Subcellular location: Cytoplasm, cytoskeleton, cilium axoneme
Gene Ontology:
Molecular function: dynein intermediate chain binding; dynein light intermediate chain binding; minus-end-directed microtubule motor activity; ATP binding
Biological process: determination of left/right symmetry; flagellated sperm motility; protein localization to motile cilium; regulation of cilium beat frequency; cilium movement involved in cell motility; microtubule-based movement; microtubule-based process
Cellular component: 9+2 motile cilium; axoneme; motile cilium; proximal portion of axoneme; dynein complex; 9+0 motile cilium; cilium
Genetic constraint (gnomAD): Loss-of-function variants: 413 observed, 491.31 expected, observed/expected ratio (o/e) 0.84, 90% interval 0.77 to 0.91. The synonymous counts are far from expectation, so gnomAD's model fits this gene poorly and the ratio says little. Missense variants: 6,746 observed, 5,395.7 expected, observed/expected ratio (o/e) 1.25, 90% interval 1.23 to 1.28. Synonymous variants: 2,380 observed, 1,925.5 expected, observed/expected ratio (o/e) 1.24, 90% interval 1.19 to 1.28.
Gene-disease validity (ClinGen):
ClinGen rates the evidence that DNAH11 causes each of these diseases.
primary ciliary dyskinesia 7 (autosomal recessive): Definitive.
Homologues: Orthologues: chimpanzee DNAH11 (99% identical), dog DNAH11 (89% identical), pig DNAH11 (88% identical), guinea pig DNAH11 (88% identical), mouse Dnah11 (85% identical), rat Dnah11 (83% identical), tropical clawed frog dnah11 (69% identical), zebrafish dnah11 (43% identical). Paralogues in human: DNAH9 (59% identical), DNAH17 (58% identical), DNAH2 (30% identical), DNAH10 (30% identical), DNAH5 (29% identical), DNAH8 (29% identical), DNAH6 (27% identical), DNAH1 (27% identical), DNAH3 (27% identical), DNAH7 (27% identical), DNAH12 (27% identical), DNAH14 (24% identical), and 3 more.
Diseases named in the same sentence as DNAH11 in open-access papers:
DNAH11 is named in the same sentence as 58 diseases in open-access papers, as found by Europe PMC text mining. Sharing a sentence is not in itself a finding about the gene and the disease. The quoted sentences say what the papers report.
primary ciliary dyskinesia (26 papers, 2014 to 2026). A rare, genetically heterogeneous, primarily respiratory disorder characterized by chronic upper and lower respiratory tract disease. "Biallelic variants in the DNAH11 gene are associated with primary ciliary dyskinesia in multiple populations, and in heterotaxy syndrome, and laterality defect." (PMID 35440622, 2022). "A heterozygous nonsense variant was found in the DNAH11, which was linked to primary ciliary dyskinesia 7 (CILD7; OMIM-P 611884)." (PMID 36140829, 2022). "Variants of DNAH11 are found also in primary ciliary dyskinesia patients with normal ciliary ultrastructure." (PMID 33574797, 2020). "Recent studies have demonstrated that mutations in other cilia dynein heavy-chain genes (such as DNAH5, DNAH9, and DNAH11) can cause primary ciliary dyskinesia (PCD)." (PMID 29843777, 2018). "Mutations in DNAH11 are associated with primary ciliary dyskinesia (PCD) (OMIM: 611884), which is an autosomal recessive disorder that leads to abnormalities in the action of the cilia lining." (PMID 30359267, 2018). "Given the high degree of conservation of DNAH11, mutations could give rise to primary ciliary dyskinesia (PCD) and asthenozoospermia." (PMID 31160482, 2019). "Diagnosis of primary ciliary dyskinesia (PCD) still remains a challenge, especially with mutations in the Dynein Arm Heavy Chain 11 (DNAH11) gene." (PMID 33243178, 2020). "In humans, DNAH11 has a role in primary ciliary dyskinesia, which is a rare condition leading to respiratory complications." (PMID 40725399, 2025). "DNAH11 encodes an ODA protein, and mutations in DNAH11 are known to cause primary ciliary dyskinesia (PCD)." (PMID 40351391, 2025). "The diagnostic genetic variant rate identified using WES was 11.1% (8/72), in which primary ciliary dyskinesia (PCD)-associated gene mutations (CCDC40, CCDC114, DNAH5, DNAH11, and ARMC4) accounted for the vast majority (n = 5)." (PMID 35518361, 2022). "As an example, DNAH11, DNAH5, DNAI1, and CCDC40 genes have been linked to primary ciliary dyskinesia." (PMID 33574797, 2020). "We herein firstly reported a case of co-occurrence of Kartagener syndrome and MMS, who had a homozygotic nonsense mutation in DNAH5 gene, and heterozygotic missense mutation in the DNAH11 gene." (PMID 32847546, 2020). "In humans, the protein participates in assembling the outer dynein arms of the sperm axoneme, and is expressed in the trachea, lung and testis; mutations in DNAH11 can give rise to primary ciliary dyskinesia (PCD) in patients with normal axonemal ultrastructure." (PMID 31160482, 2019). "Pathogenic mutations were identified in three families (n = 3/33, 9.1%), including mutations in DNAH11, RAF1 and CHD7, which were associated with primary ciliary dyskinesia, Noonan syndrome, and CHARGE syndrome, respectively." (PMID 30359267, 2018). "Promising results have been achieved in cells from patients with the motile ciliopathy primary ciliary dyskinesia where ciliation was restored on replacement of the wild-type DNAH11 sequence." (PMID 29487844, 2018). "Jennifer Keynton (MRC Harwell, UK) presented a new mutant mouse model for primary ciliary dyskinesia (PCD) carrying a mutation in the axonemal dynein heavy chain (Dnah11), called lrm5, which shows normal ciliary beat frequency in the trachea, but accelerated and abnormal cilia motion in the node." (PMID 25974046, 2015). "The dynein axonemal heavy chain 11 gene (DNAH11) pathogenic variants are responsible for primary ciliary dyskinesia 7, with or without left-right asymmetry disorder." (PMID 42102130, 2026). "The combined mutation of DNAH5 and DNAH11 may lead to the overlapping dysfunction of motile and nonmotile cilia, which contribute to the co-occurrence of Kartagener syndrome and moyamoya syndrome." (PMID 32847546, 2020).
primary ciliary dyskinesia (continued). "More importantly, DNAH9, DNAH11, PIH1D3, and SPAG1 were classified as primary ciliary dyskinesia (PCD) disease genes typically with AR inheritance; PIH1D3 follows X-linked recessive (XLR) inheritance." (PMID 35877578, 2022).
male infertility (11 papers, 2009 to 2025). The inability of the male to effect fertilization of an ovum after a specified period of unprotected intercourse. "We identified a male infertility patient with AZS carrying a compound heterozygous mutation in the DNAH11 gene." (PMID 41398886, 2025). "Although DNAH11 abnormality was associated with male infertility recently, a woman with primary infertility has been reported to carry homozygous pathogenic variants in DNAH11." (PMID 40142748, 2025). "A systematic search of the PubMed database using the keywords “DNAH11” and “male infertility” identified 9 cases from 8 independent pedigrees, involving 12 distinct DNAH11 gene mutations." (PMID 41398886, 2025). "Future studies will focus on in-depth mechanistic analyses to further clarify the pathogenic pathways linking DNAH11 mutations to male infertility." (PMID 41398886, 2025). "This study provides new genetic evidence supporting the causal relationship between DNAH11 mutations and male infertility, thereby contributing to the improved diagnosis and genetic counseling of affected individuals." (PMID 41398886, 2025). "Approximately 90% of men with PCD are diagnosed with asthenozoospermia and two reports have involved a link between DNAH11 mutations and male infertility." (PMID 31160482, 2019). "Mutations in dynein genes (DNA11, DNAH5, and DNAH11) have been linked to a common cause of male infertility in humans, asthenozoospermia, which is inherited in a dominant sex-specific manner." (PMID 19503617, 2009). "Taken together, these data suggested that DNAH11 deficiency causing male infertility with MMAF may be related to a defect in ODA assembly resulting from the reduced expression of ODA‐associated proteins." (PMID 40351391, 2025). "For humans, only two studies have reported the single nucleotide polymorphisms of DNAH11 in patients with asthenozoospermia, suggesting that DNAH11 mutations may be a risk factor for male infertility." (PMID 40351391, 2025). "However, current evidence regarding DNAH11 mutations in male infertility remains limited, warranting further exploration of their pathogenic mechanisms." (PMID 41398886, 2025). "Therefore, additional genetic studies are needed to further elucidate the pathogenic mechanisms of DNAH11 in male infertility." (PMID 41398886, 2025). "We found that DNAH11 gene polymorphisms display strong associations with asthenozoospermia, and may contribute to an increased risk of male infertility in Chinese patients." (PMID 31160482, 2019). "We found that DNAH11 polymorphisms display strong associations with asthenozoospermia, and may contribute to an increased risk of male infertility in Chinese patients." (PMID 31160482, 2019). "Based on this evidence, we propose that DNAH11 mutations demonstrate notable phenotypic heterogeneity, with some carriers developing PCD and others exhibiting only male infertility." (PMID 41398886, 2025). "In this study, we identified a biallelic variation in the DNAH11 gene in a patient with male infertility due to AZS." (PMID 41398886, 2025). "In summary, the compound heterozygous DNAH11 mutations c.1174del and c.3766-8A > G may represent the pathogenic cause of AZS in this male infertility patient." (PMID 41398886, 2025). "Combining the current findings with previous reports, among ten male infertility patients carrying DNAH11 mutations, 9 exhibited no clinical manifestations of PCD, while only one presented with mild PCD-related symptoms, including chronic cough and bronchiectasis." (PMID 41398886, 2025). "In conclusion, our study first identified two biallelic DNAH11 variations as a new genetic factor of MMAF and further provided adequate genetic and therapeutic counselling for male infertility." (PMID 40351391, 2025). "However, mutations in DNAH5, DNAH11, and DNAI1 also lead to male infertility due to isolated non-syndromic asthenozoospermia." (PMID 36726469, 2022).
situs inversus (8 papers, 2019 to 2024). A congenital condition in which there is complete right-to-left reversal of the position of the major thoracic and abdominal organs (that is, they are arranged in a mirror image of the normal positioning). "Indeed, a recent case report of mutations in the dynein heavy chain genes, DNAH5 and DNAH11 has raised the possibility of a link between situs inversus and developmental dyslexia." (PMID 35873488, 2022). "The third patient with situs inversus had the CFAP298 mutation, which was linked to hyperkinetic CBP, as shown in other variants, such as DNAH11." (PMID 36980814, 2023). "The final evidence includes features of bile duct inflammation in the liver from DNAH11–/– mice, which are known to exhibit situs inversus." (PMID 33192543, 2020). "Variants in other genes such as DNAL1 (OMIM: 610062), DNAI1 (OMIM: 604366) and DNAH11 (OMIM: 603339), which are coding for dynein compartments, are known to cause situs inversus-like phenotypes." (PMID 30679815, 2019). "Therefore, we asked whether previously reported situs inversus in the Dnah11–/– null mouse was accompanied by biliary pathology." (PMID 33192543, 2020).
asthenozoospermia (7 papers, 2009 to 2025). "By sequencing, compound heterozygous DNAH11 variants c.9484-1 G>T and c.12428 T>C were associated with one of the 87 patients with asthenozoospermia." (PMID 31160482, 2019). "Here, we screened 87 patients with asthenozoospermia for variants in DNAH11 and discovered compound heterozygous DNAH11 variants in one patient with asthenozoospermia using high-throughput targeted gene sequencing technology." (PMID 31160482, 2019). "In the present study, 87 patients with idiopathic asthenozoospermia for variants in DNAH11 were screened by using high-throughput targeted gene sequencing technology." (PMID 31160482, 2019). "To date, few studies have reported on the association between variants in DNAH11 and asthenozoospermia." (PMID 31160482, 2019). "In our study, one of 87 asthenozoospermia patients was detected as carrying DNAH11 compound heterozygous variants (c.9484-1 G>T, c.12428 T>C)." (PMID 31160482, 2019).
breast carcinoma (6 papers, 2022 to 2024). "DNAH11, a member of the dynein heavy chain family encoding a ciliary outer dynein arm protein, has been implicated as a predisposition gene in breast cancer families." (PMID 38970307, 2024). "A variant of the DNAH11 gene, rs2285947, is a potential risk factor for ovarian and breast cancer progression." (PMID 36675580, 2023). "Verma reported that the rs2285947 variant of the DNAH11 gene predicted poor prognosis for ovarian and breast cancer patients." (PMID 36581992, 2022). "A few reports have linked variants (other than those observed in the current study) in DNAH11 with breast cancer risk, but these reports were based on comparatively small sample sizes (c.2081_2082del (p.Val694Glyfs*2)) and studies involving specific populations (G > A (rs2494938-India))." (PMID 35884425, 2022). "According to COSMIC, the DNAH11 variant is associated with esophageal carcinoma, while CFH is linked to breast cancer." (PMID 38970307, 2024). "Of these twenty, three showed evidence of association with LoF variants for overall breast cancer (ZFAND1, TYRO3, TMEM206/PACC1), and a further six with breast cancer subtypes (DNAH11, PARP2, LAMC3, MTMR11, EPN3, SLC22A10)." (PMID 35884425, 2022). "Additionally, mutations in DNAH11 have been reported in BRCA1‐ and BRCA2‐negative breast cancer families, further supporting its role in cancer predisposition." (PMID 38970307, 2024). "We found nominal evidence of association with breast cancer overall for LoF variants in three genes (ZFAND1, TMEM206/PACC1, and TYRO3), with ER-negative breast cancer in two genes, DNAH11 and PARP2, and with ER-positive disease in four genes LAMC3, MTMR11, EPN3, and SLC22A10." (PMID 35884425, 2022).
ciliopathy (6 papers, 2011 to 2026). A genetic disorder of the cellular cilia or the cilia anchoring structures, the basal bodies, or of ciliary function. "The phenotypes observed in these patients are consistent with typical/probably atypical PCD or DNAH11-associated ciliopathy, although functional validation is needed to confirm variant pathogenicity." (PMID 42102130, 2026). "Loss-of-function mutations in DNAH9, which is a paralog of DNAH11, cause a motile ciliopathy characterized by LRA defects and mild respiratory beating defects in the distal ciliary region." (PMID 33139725, 2020). "Especially the mutations of the gene dynein axonemal heavy chain 11 (DNAH 11) are thought to be associated with ciliopathy and SI." (PMID 21813017, 2011). "DNAH11 encodes a ciliary outer dynein arm protein, a member of the dynein heavy chain (DNAH) family and was associated with one of the main significant pathways, ciliopathies (WP4803)." (PMID 37444425, 2023).
Infertility (6 papers, 2020 to 2025). "In our cohort, the female patient with DNAH11-negative staining with infertility issues, consistent with previous reports of primary infertility in individuals with DNAH11 mutations." (PMID 40142748, 2025). "Intriguingly, our study first identified two biallelic mutations in DNAH11 in two unrelated infertile patients with an MMAF phenotype, who denied suffering from any symptoms of PCD." (PMID 40351391, 2025). "Conversely, for DNAH11, we reported only fertile individuals, whereas previous publications showed both fertile and infertile individuals." (PMID 38962571, 2024). "Having become an adult recently, she was diagnosed with infertility and, in current study respiratory epithelial cells, displayed DNAH11 negative staining." (PMID 40142748, 2025).
congenital heart disease (4 papers, 2019 to 2024). A heart disease that is present at birth. "DNAH11 gene variants have been associated with congenital heart disease and are involved in respiratory cilia motility (PMID: 26729821, PMID: 22184204, PMID: 31040315)." (PMID 34354115, 2021).
bronchiectasis (3 papers, 2021 to 2025). Segmental, irreversible dilation of the bronchial tree resulting in the accumulation of secretions which leads to obstruction. "No obvious chronic airway infection symptoms or signs, such as recurrent rhinitis, sinusitis, otitis media, bronchitis, frequent pneumonias, or bronchiectasis were observed in the two family members having the DNAH11 compound heterozygous variants." (PMID 34133440, 2021). "The compound heterozygous DNAH11 missense variants, c.4306C>T (p.(Arg1436Trp)) and c.6118C>T (p.(Arg2040Cys)), were reported in a patient with bronchiectasis, a clinical manifestation of PCD." (PMID 34133440, 2021).
Dextrocardia (3 papers, 2021 to 2025). The heart is located in the right hand sided hemithorax. "Remarkably, three probands carrying DNAH11 variants exhibited dextrocardia." (PMID 40406060, 2025).
otitis media (3 papers, 2021 to 2024). Inflammation of the anatomical structures of the middle ear, which is most often caused by an infectious process. "An 11-year-old girl PCD-#07 II1, who suffered from chronic upper airway disorders, otitis media, and atelectasis, proved to be a compound heterozygote for two frameshifts in DNAH11." (PMID 39180133, 2024).
Heterotaxy (2 papers, 2019 to 2022). An abnormality in which the internal thoraco-abdominal organs demonstrate abnormal arrangement across the left-right axis of the body. "We considered the 98 CHD cases as controls, fisher’s exact test revealed that DNAH11 mutations can significantly increase the risk of developing CHD/HTX syndrome, indicating a significant association of DNAH11 mutations with CHD and heterotaxy syndrome." (PMID 31040315, 2019).
Hydrocephalus (2 papers, 2012 to 2021). Hydrocephalus is an active distension of the ventricular system of the brain resulting from inadequate passage of CSF from its point of production within the cerebral ventricles to its point of absorption into the systemic circulation. "The occurrence of PCD and hydrocephalus has been reported in the past and has been shown to be associated with mutations in various genes (DNAI1, DNAH5, DNAH11, DNAI2, KTU, and RSPH9/4A)." (PMID 33999288, 2021).
sarcoidosis (2 papers, 2018 to 2025). Sarcoidosis is a multisystemic disorder of unknown cause characterized by the formation of immune granulomas in involved organs. "Whole exome sequencing identified that the protein DNAH11 may contribute to the formation of the characteristic lesion through regulating G-proteins in pediatric sarcoidosis." (PMID 41279897, 2025).